BRD4 (bromodomain containing 4)
Diseases named in the same sentence as BRD4 in open-access papers (continued):
Sharing a sentence is not in itself a finding about the gene and the disease.
peripheral neuropathy (2 papers, 2021 to 2022). A disorder affecting the peripheral nervous system. "At analgesic doses, SUM52 reduced the spinal overexpression of HDAC1 and BRD4 induced by the peripheral neuropathy." (PMID 35501470, 2022). "BRD4 inhibitors also have a protective effect against vincristine induced peripheral neuropathy by reducing inflammation." (PMID 34336890, 2021).
psychiatric disorder (2 papers, 2024 to 2025). A disorder characterized by behavioral and/or psychological abnormalities, often accompanied by physical symptoms. "A high incidence of psychiatric disorders has been observed in patients with BRD4 loss-of-function variants." (PMID 41300558, 2025). "BRD4 initiates gene transcription by recognizing acetylated histones, which are associated with many psychiatric disorders." (PMID 38988837, 2024).
respiratory diseases (1 paper, 2024). "In respiratory diseases like RSV, BRD4 functions as a potent co-activator of interferon-stimulated genes (ISGs), initiating pro-inflammatory responses essential for viral defense." (PMID 39066258, 2024).
BRD4 also shares sentences with these, for which no sentence is quoted: bacterial infection (5 papers); myelodysplastic syndrome (5); alveolar rhabdomyosarcoma (4); cutaneous melanoma (4); oral squamous cell carcinoma (4); stomach adenocarcinoma (3); uveal melanoma (3); Chronic Lymphocytic Leukemia (2); chronic rhinosinusitis (2); depression (2); diabetic kidney disease (2); Hepatitis (2); Merkel cell carcinoma (2); non-alcoholic steatohepatitis (2); renal carcinoma (2); retinopathy (2); T-cell leukemia (2); abdominal aortic aneurysm (1); ACTHomas (1); acute coronary syndrome (1); acute respiratory distress syndrome (1); adenoma (1); alcohol (1); ameloblastoma (1); amnesia (1); amyloid (1); anaplastic thyroid cancer (1); anemia (1); angiosarcoma (1); aortic aneurysm (1).
A further 97 diseases each share a sentence with BRD4 in 1 paper.